HNRNPC (heterogeneous nuclear ribonucleoprotein C)
Diseases named in the same sentence as HNRNPC in open-access papers (continued):
Sharing a sentence is not in itself a finding about the gene and the disease.
cervical cancer (5 papers, 2022 to 2025). A primary or metastatic malignant neoplasm involving the cervix. "The expression of hnRNPC is also overexpressed in cervical cancer and significantly contributes to lymphatic metastasis." (PMID 41429980, 2025). "These collective and compelling findings establish hnRNPC as an indispensable downstream mediator through which INTS13 exerts its pro-cancerous effects within cervical cancer cells." (PMID 41429980, 2025). "Conversely, the ectopic overexpression of INTS13 (oeINTS13-Slc1) in pCCa-1 cells resulted in a marked elevation in both hnRNPC mRNA and protein levels, thereby confirming that INTS13 positively regulates hnRNPC expression in pCCa-1 cervical cancer cells." (PMID 41429980, 2025). "Here, we found that INTS13-promoted cervical cancer growth is mediated through its effect on hnRNPC expression." (PMID 41429980, 2025). "We revealed higher levels of ZC3H13, WTAP, HNRNPC, YTHDF3, and VIRMA were significantly associated with worse outcomes in CESC (HR > 1, blue background), while YTHDC1, YTHDF1 were protective factors of cervical cancer (HR < 1, orange background)." (PMID 35581263, 2022). "Finally, in vivo animal models confirmed that targeted silencing of INTS13 significantly impeded cervical cancer xenograft growth in nude mice, reduced cellular proliferation, and augmented apoptosis, consistently accompanied by a reduction in hnRNPC expression." (PMID 41429980, 2025). "We identified hnRNPC as a critical downstream effector, demonstrating that INTS13 regulates its expression in pCCa-1 primary cervical cancer cells." (PMID 41429980, 2025). "YTHDC1 and YTHDF1 have anti-cancer effects in cervical cancer, while ZC3H13, WTAP, HNRNPC, YTHDF3 and VIRMA have tumor-promoting effects in cervical cancer." (PMID 35581263, 2022). "Mechanistically, we identified heterogeneous nuclear ribonucleoprotein C (hnRNPC) as a critical downstream effector, with INTS13 regulating hnRNPC expression, and the restoration of hnRNPC effectively reversing the anti-cervical cancer effects observed upon INTS13 silencing." (PMID 41429980, 2025).
esophageal squamous cell carcinoma (5 papers, 2021 to 2024). Esophageal squamous cell carcinoma (ESCC) is a type of esophageal carcinoma (EC) that can affect any part of the esophagus, but is usually located in the upper or middle third. "METTL3, WTAP, IGF2BP3, YTHDF1, HNRNPA2B1 and HNRNPC were markedly increased in esophageal squamous cell carcinoma (ESCC) and positively related to the expression of PD-1, whose copy number dynamically affects the enrichment of tumor-infiltrating immune cells." (PMID 36225914, 2022). "HNRNPC is also highly expressed in pancreatic adenocarcinoma and esophageal squamous cell carcinoma (ESCC), and can regulate the TIME." (PMID 39028290, 2024).
thyroid cancer (5 papers, 2021 to 2023). "Consistent with their work in other cancers, our results suggest that HNRNPC functions as an oncogene in thyroid carcinoma." (PMID 34281544, 2021). "In particular, HNRNPC, RBM15B, IGFBP2, and ELF3 were upregulated, while the other 12 genes were downregulated in thyroid cancer tissues." (PMID 36389678, 2022). "Most of the key m6A regulators were positively correlated to iodide-handling genes in thyroid cancer, but IGF2BP2, HNRNPC, WTAP, and RBM15B were negatively correlated to iodide-handling genes, and the correlation between IGF2BP2 and iodide-handling gene was the strongest." (PMID 35267576, 2022).
clear cell renal cell carcinoma (4 papers, 2024). "In clear cell renal cell carcinoma, circPPAP2B interacts with HNRNPC to facilitate nuclear translocation, and circPPAP2B modulates the interaction between HNRNPC and splicing factors to regulate pre-mRNA alternative splicing." (PMID 39567496, 2024).
colon adenocarcinoma (4 papers, 2020 to 2025). "Similarly, it has been revealed that HNRNPC is abundantly expressed in colon adenocarcinoma and might play a vital role in the progression of colon adenocarcinoma." (PMID 33193582, 2020).
non-small cell lung carcinoma (4 papers, 2020 to 2025). A group of at least three distinct histological types of lung cancer, including non-small cell squamous cell carcinoma, adenocarcinoma, and large cell carcinoma. "Enhanced HNRNPC expression is strongly associated with tumor stage advancement and metastasis development, and HNRNPC is considered a predictor for the response to immunotherapy in non-small cell lung cancer cells." (PMID 40236649, 2025). "KHSRP (KH-type splicing regulatory protein) could promote invasion and metastasis of non-small-cell lung cancer by interacting with HNRNPC." (PMID 35897085, 2022).
amyotrophic lateral sclerosis (3 papers, 2024 to 2025). Amyotrophic lateral sclerosis (ALS) is a neurodegenerative disease characterized by progressive muscular paralysis reflecting degeneration of motor neurons in the primary motor cortex, corticospinal tracts, brainstem and spinal cord. "Among these genes, HNRNPA1, HNRNPC, and HNRNPU are involved in RNA processing and have been linked to neurodegenerative diseases such as amyotrophic lateral sclerosis and frontotemporal dementia." (PMID 40943121, 2025). "Our results reveal significant nuclear loss of hnRNPD, hnRNPC and hnRNPA1 in the frontal cortex of frontotemporal lobar degeneration compared to amyotrophic lateral sclerosis but not in the motor cortical neurons or Betz cells of amyotrophic lateral sclerosis cases." (PMID 39670112, 2024).
brain tumor (3 papers, 2020 to 2021). "The experimental results show that the expression levels of HNRNPC are higher in highly aggressive cancer cells and are elevated along with the brain tumour grade." (PMID 35004679, 2021). "Silencing of hnRNPC can inhibit migratory and invasive activities by promoting miRNA-21 in brain tumor cells." (PMID 33329703, 2020).
papillary renal cell carcinoma (3 papers, 2021 to 2025). A rare subtype of renal cell carcinoma, arising from the renal tubular epithelium and showing a papillary growth pattern, which typically manifests with hematuria, flank pain, palpable abdominal mass or nonspecific symptoms, such as fatigue, weight loss or fever. "Accumulated evidence has proved that HNRNPC, which acts as a m6A reader, plays an essential role in the promotion of cancer occurrence and development; nevertheless, the role of HNRNPC in papillary renal cell carcinoma remained to be discovered." (PMID 35502201, 2022). "Finally, in kidney papillary carcinoma (KIRP), the signature included YTHDC2, IGF2BP2, DNMT3B, TRMT6, HNRNPC, and NSUN5." (PMID 40565233, 2025).
sarcoma (3 papers, 2018 to 2025). A usually aggressive malignant neoplasm of the soft tissue or bone. "Human regulatory proteins HNRNPA1 (heterogeneous nuclear ribonucleoprotein A1), HNRNPC, HNRNPL, HuR (human antigen R), and protein LIN28A (lin-28 homolog A) were predicted to bind ebv-sisRNA-1 and/or ebv-sisRNA-2; FUS (fused in sarcoma) was predicted to associate with ebv-sisRNA-2." (PMID 29458410, 2018). "Male patients showed elevated HNRNPC expression levels in LUAD, HNSC, MESO, and Rectum adenocarcinoma (READ), whereas female patients exhibited high expression levels in Sarcoma (SARC), KIPAN, KIRC, and LIHC." (PMID 39735682, 2025).
testicular germ cell tumor (3 papers, 2020 to 2022). A germ cell tumor arising from the testis. "HNRNPC expression was also shown to be related to cancer-associated cell infiltration, most notably in uveal melanoma, testicular germ cell tumors, and thymoma." (PMID 35344508, 2022). "Some studies have shown that METTL3, ALKBH5, YTHDC1, YTHDF1, YTHDF2, and HNRNPC are the main m6A-related genes in type II testicular germ cell tumors." (PMID 32258108, 2020).
viral infection (3 papers, 2022 to 2025). "To determine whether hnRNPC responds to viral infection, we examined hnRNPC expression in zebrafish cell lines after infection with SVCV." (PMID 39994817, 2025). "Several studies have revealed that hnRNPC plays an important role in viral infection." (PMID 39994817, 2025). "However, the underlying mechanisms by which hnRNPC modulates virus infections have not been fully elucidated." (PMID 39994817, 2025).
cervical squamous cell carcinoma (2 papers, 2022 to 2025). A squamous cell carcinoma arising from the cervical epithelium. "The results showed that the expressions of WTAP were downregulated; and the expressions of four m6A-RMRs such as HNRNPA2B1, IGF2BP2, FMR1, and HNRNPC were upregulated in patients with preinvasive and invasive cervical squamous cell carcinomas compared with normal controls." (PMID 35211628, 2022). "Subsequent analyses suggested a potential correlation between elevated HNRNPC expression and reduced disease-free survival (DFS) in ACC, KIRP, KIPAN, LIHC, Cervical Squamous Cell Carcinoma (CESC), and Mesothelioma (MESO) patients." (PMID 39735682, 2025).
COVID-19 (2 papers, 2022). A disease caused by infection with severe acute respiratory syndrome coronavirus 2. "Of note, we observed numerous DTU genes involved in RNA splicing, with 10 genes (e.g. HNRNPC, SNRPD3, QKI, and LUC7L2) increased major transcript usage and 18 genes (e.g. SNRNP48, NCBP1, CELF2, RALY, and PABPC1) decreased major transcript usage in the COVID-19 patients." (PMID 35421082, 2022).
endometrial carcinoma (2 papers, 2021 to 2025). A malignant tumor arising from the epithelium that lines the cavity of the uterine body. "In endometrial cancer patients, higher HNRNPC, YTHDC2, WTAP, VIRMA, IGF2BP3, and HNRNPA2B1 expression is closely associated with worse outcomes and advanced stage." (PMID 34616742, 2021). "More recently, the levels of YTHDC2, HNRNPC, and VIRMA were suggested to be negatively correlated, whereas WTAP was positively correlated, with MHC molecules in endometrial cancer." (PMID 34616742, 2021).
epilepsy (2 papers, 2022 to 2025). A brain disorder characterized by episodes of abnormally increased neuronal discharge resulting in transient episodes of sensory or motor neurological dysfunction, or psychic dysfunction. "For instance, whilst HNRNpc was expressed at a lower level in keeping with the findings of the integrated investigation, in patients with epilepsy WTAP and YTHDC1 displayed higher expression levels." (PMID 40530256, 2025). "The qRT-PCR results indicated that WTAP and YTHDC1 have higher expression levels in patients with epilepsy, while HNRNPC was expressed to a lower level, which is consistent with our integrated analysis." (PMID 36468034, 2022). "The random forest (RF) model was applied to the screening, and seven m6A regulators (HNRNPC, WATP, RBM15, YTHDC1, YTHDC2, CBLL1, and RBMX) were selected as the candidate genes for predicting the risk of epilepsy." (PMID 36468034, 2022). "Among these, seven genes-WTAP, HNRNPC, RBM15, CBLL1, YTHDC1, YTHDC2, and RBMX-exhibited distinct expression patterns between healthy individuals and those with epilepsy." (PMID 40530256, 2025). "We found a positive correlation between the expression of HNRNPC, RBMX, and RBM15 in patients with epilepsy." (PMID 36468034, 2022). "Firstly, we analyzed the expression of 17 m6A-related genes extracted from a public dataset and found that seven of them (HNRNPC, WTAP, RBM15, YTHDC1, YTHDC2, CBLL1, and RBMX) were differentially expressed between patients with epilepsy and healthy individuals." (PMID 36468034, 2022).
infertile (2 papers, 2023 to 2025). "This suggests that reduced expression of HNRNPA2B1 and HNRNPC in stromal cells—key components of endometrial tissue—may serve as diagnostic markers for EMS-related infertility." (PMID 39739380, 2025). "In summary, this study proposes HNRNPA2B1 and HNRNPC as potential biomarkers for EMS-related infertility." (PMID 39739380, 2025). "The results showed that HNRNPA2B1 and HNRNPC expression levels were significantly higher in endometrial immune cells from infertile EMS patients but lower in stromal cells." (PMID 39739380, 2025). "The results indicated that the expression levels of HNRNPA2B1 and HNRNPC in endometrial tissue from normal fertile women were significantly higher than those in ovarian tissue from infertile women with EMS." (PMID 39739380, 2025). "In summary, the findings suggest that HNRNPA2B1 and HNRNPC could serve as potential biomarkers for EMS-related infertility." (PMID 39739380, 2025). "In summary, this study predicted that HNRNPA2B1 and HNRNPC could serve as potential biomarkers of EMS-related infertility." (PMID 39739380, 2025). "Additionally, HNRNPA2B1 and HNRNPC have potential as biomarkers for diagnosing or monitoring EMS-related infertility." (PMID 39739380, 2025). "The expression levels of HNRNPA2B1 and HNRNPC in various cell types within the eutopic endometrium of normal fertile women and infertile patients with EMS were analyzed." (PMID 39739380, 2025). "Finally, clinical samples of eutopic endometrium from normal fertile women and infertile ovarian patients with EMS were collected, and immunohistochemical staining was used to analyze the expression levels of HNRNPA2B1 and HNRNPC." (PMID 39739380, 2025).
Multiple Myeloma (2 papers, 2022 to 2023). "Paired differential analysis identified three of them (hnRNPA2B1, YTHDF3 and hnRNPC) are significantly upregulated in plasma cells of myeloma patients compared to normal plasma cells (Fold Change > 2)." (PMID 36451863, 2022). "Additionally, we found expression of MYC, 4EBP1, LARP1, and hnRNPC to be significantly increased in primary samples from newly diagnosed multiple myeloma (NDMM) patients compared to plasma cells (PC) from healthy donors." (PMID 38067212, 2023).
neuroblastoma (2 papers, 2021 to 2023). Neuroblastoma (NB) is the most common solid, extracranial childhood tumor. "We observed the same cooperative effect of DDX5/DDX17 and HNRNPC on exon inclusion in the neuroblastoma SH-SY5Y cell line." (PMID 38128543, 2023).
oral cancer (2 papers, 2022 to 2023). "In this study, we show that CYTOR regulates ZEB1 via HNRNPC-mediated mRNA stabilization to alter energy metabolism, ultimately facilitating metastasis of oral cancer cells." (PMID 35963855, 2022). "Next, we transfected the HN6 and Cal27 oral cancer cell lines with small interfering RNAs or a pcDNA plasmid to knock down or overexpress HNRNPC, respectively." (PMID 35963855, 2022). "The results showed that deletion of either CYTOR or HNRNPC promoted the degradation of ZEB1 mRNAs in oral cancer cells." (PMID 35963855, 2022). "To better understand the HNRNPC downstream regulation, we first conducted RNA-seq analysis of stable HNRNPC KD and negative control (NC, scrambled insert) oral cancer cells, which identified that HNRNPC-KD resulted in dysregulation of 1180 genes (609 up- and 571 downregulated)." (PMID 35963855, 2022).
osteoarthritis (2 papers, 2023 to 2024). A noninflammatory degenerative joint disease occurring chiefly in older persons, characterized by degeneration of the articular cartilage, hypertrophy of bone at the margins and changes in the synovial membrane. "This showed that infiltrating MDSCs were increased in osteoarthritis, which was closely related to the expression of RBM15B and HNRNPC." (PMID 36777725, 2023). "However, the changes in HNRNPC in osteoarthritis have still not been specifically reported." (PMID 36777725, 2023).
pancreatic ductal adenocarcinoma (2 papers, 2022 to 2023). An infiltrating adenocarcinoma that arises from the epithelial cells of the pancreas. "hnRNPC‐dependent alternative splicing accelerates the liver metastasis of pancreatic ductal adenocarcinoma." (PMID 37850412, 2023). "Specifically, hnRNPC facilitates the alternative splicing of TAF8 by binding to TAF8 mRNA, resulting in the production of the pro‐metastatic TAF8 S isoform in pancreatic ductal adenocarcinoma." (PMID 37850412, 2023). "In this study, we found that heterogeneous nuclear ribonucleoprotein C (hnRNPC), a RBP, is highly expressed in pancreatic ductal adenocarcinoma (PDAC) tissues and cells." (PMID 35355828, 2022).
Sepsis (2 papers, 2023). Sepsis is defined as life-threatening organ dysfunction caused by a dysregulated host response to infection. "In this predictive nomogram, the expression levels of FTO, HNRNPC, RBMX, YTHDC1, LRPPRC, and RBM15B were negatively associated with the risk score of patients with sepsis and were regarded as protective factors in sepsis." (PMID 36781867, 2023). "Further research also confirmed the protective effects of FTO, HNRNPC, YTHDC1, and RBM15B in sepsis patients." (PMID 38112620, 2023). "Trials have demonstrated a substantial correlation between m6A regulators including ALKBH5, HNRNPC, KIAA1429, WTAP, and YTHDF2 and 28-day cumulative mortality in sepsis patients." (PMID 38112620, 2023).
uveal melanoma (2 papers, 2022 to 2025). A melanoma derived from melanocytes of the uveal tract. "Additionally, our Cox regression analysis demonstrated a robust correlation exists between elevated HNRNPC expression and unfavorable progression-free survival (PFS) in ACC, LIHC, KIRP, Diffuse Large B-Cell Lymphoma (DLBC), HNSC, SKCM, Uveal Melanoma (UVM), LUAD, and KICH." (PMID 39735682, 2025).
adrenal cancer (1 paper, 2021). A carcinoma involving a adrenal gland. "Conversely, overexpression of HNRNPC facilitated the proliferation, migration and invasion of adrenal cancer cells." (PMID 33952721, 2021).
adrenocortical carcinoma (1 paper, 2023). "HNRNPC plays a cancer-promoting role in adrenocortical carcinoma (ACC) progression, and experiments have demonstrated that HNRNPC promotes the proliferation, migration, and invasion of H295R and SW13 cells and influences the immune microenvironment." (PMID 36777725, 2023).
Alzheimer disease (1 paper, 2021). A progressive, neurodegenerative disease characterized by loss of function and death of nerve cells in several areas of the brain leading to loss of cognitive function such as memory and language. "In Alzheimer’s disease, hnRNPC promotes APP translation and stabilizes the APP precursors mRNA, which could suggest that increasing hnRNPC levels may promote Aβ secretion." (PMID 34924950, 2021).
atherosclerosis (1 paper, 2023). A disease characterized by the build-up of fatty material and calcium deposition in the arterial wall resulting in partial or complete occlusion of the arterial lumen. "We may, hence, hypothesize that hnRNPC and hnRNPA2B1 downregulation could reduce the deleterious effects that m6A increase has in atherosclerosis RNA metabolism and alternative maturation." (PMID 37570694, 2023).
Azoospermia (1 paper, 2025). Absence of any measurable level of sperm,whereby spermatozoa cannot be observed even after centrifugation of the semen pellet. "Among the hnRNP family, loss of hnRNPC, which is a potential m6A reader, leads to azoospermia, implying the critical role of m6A-binding proteins in male fertility performance." (PMID 41436426, 2025).
chronic obstructive pulmonary disease (1 paper, 2021). A chronic and progressive lung disorder characterized by the loss of elasticity of the bronchial tree and the air sacs, destruction of the air sacs wall, thickening of the bronchial wall, and mucous accumulation in the bronchial tree. "In a cigarette smoke-induced chronic obstructive pulmonary disease (COPD) animal model, HNRNPC was overexpressed in the lungs of cigarette smoke-exposed mice." (PMID 34555052, 2021).
coloboma (1 paper, 2025). An abnormality in which a part of a structure in one or both eyes is missing. "On the other hand, excluding the two affected subjects with the Arg99Gln amino acid change, none of the subjects with LP/P variants in HNRNPC have been reported to show cochlear aplasia and coloboma." (PMID 40004505, 2025).